CD4 (CD4 molecule)
Diseases named in the same sentence as CD4 in open-access papers (continued):
Sharing a sentence is not in itself a finding about the gene and the disease.
tumor (continued). "In responders post-treatment, PD-1+ CD4+ T cells increase GZMB expression and move closer to tumor cells, similar to the granzyme-perforin-dependent tumor-killing mechanism used by cytotoxic CD8+ T cells." (PMID 34795254, 2021). "BT942 treatment resulted in higher increase in CD45+, CD3+T, CD4+ and CD8+T percentage in tumor at early or late phase treatment experiment when compared with vehicle or BA9 treatment." (PMID 34824364, 2021). "The densities of CD3+, CD4+, CD8+, CD45RO+, and CD56+ immune cells in tumor stroma were assessed in 372 patients." (PMID 34572935, 2021). "There was a significant increase in the levels of tumor‐infiltrating CD3+ cells, in which the CD8+/CD4+ ratios were greatly raised." (PMID 34766145, 2021). "Lymphocytes including NK cells, NKT cells, CD4+ T, and CD8+ T cells and B-cells are closely related to tumor immunity." (PMID 34355011, 2021). "We isolated macrophages, CD4+ T cells, and CD8+ T cells from the tumor as well as from normal lung tissue of 11 patients diagnosed with NSCLC." (PMID 33918618, 2021). "Overall, the in vitro stimulation studies demonstrate that multimodal immunotherapies tested can induce peripheral CD4+ and CD8+ T cell activity in the 4T1 tumor model." (PMID 33602696, 2021). "It has been shown that anti-CCL2 antibodies blocking the effects of CCL2 such as reducing MDSC, increasing CD4+ and CD8+ T cell infiltration, and promoting IFNy secretion can enhance the tumor immune effect of PD-1 in treating lung cancer in mice." (PMID 34603645, 2021). "Between two different clusters, the ICI gene-B subgroup obtained a higher immune score, and several densities of anti-tumor cells (i.e., plasma cells, M1 Macrophages, CD8+ T cells, activated CD4+ T cells, etc.), which was termed as activated immune phenotype." (PMID 34512634, 2021). "Vaccines containing both CD4 and CD8 epitopes promote Teff: Treg ratios, increase tumor infiltrating lymphocytes and inhibit tumor growth." (PMID 34806028, 2021). "In the study, artemisinin was shown to significantly decrease TGF-β mRNA levels and populations of MDSCs and Treg cells within the tumor, while increasing TNF-α mRNA levels, CD4+ interferon gamma-expressed (IFN-γ+) T cells, and cytotoxic T lymphocytes." (PMID 34948368, 2021). "B cells can directly present tumor-related antigens to CD4 + T and CD8 + T cells to exert antitumor immunity or directly kill tumor cells." (PMID 34484330, 2021). "When the tumor reached ~ 1 cm3, 80% TIL Treg cells but only 35% splenic Treg cells from an individual mouse displayed the eTreg phenotype (CD62LloCD44hiFoxp3+CD4+)." (PMID 34798898, 2021). "Monocytes and anti-tumor lymphocyte subsets such as CD8+ T cells, memory CD4+ T cells, and naive B cells had a higher level of infiltration in gene cluster B, while activated NK cells and mast cells infiltrated more abundantly in gene cluster A." (PMID 34616403, 2021). "In contrast, CD4+ and CD8+-depleted mice showed an accelerated tumor growth, reaching a maximum growth by days 65 and 47, respectively, and a mortality rate of 100% in both treatments." (PMID 33717073, 2021). "Unfortunately, the tumor microenvironment (TME) is largely immunosuppressive, with the predominant CD4+ T cell population found in tumors being regulatory T cells." (PMID 33809259, 2021). "The populations of TILs (CD4+ and CD8+) and cytotoxic TILs (CD8+granzyme B+) in primary and distant tumor tissues and spleen of SPNpro-injected mice were higher than that of SPN-1- or SPN-2-injected mice after NIR photoirradiation." (PMID 34006860, 2021). "We have recently performed transcriptomic profiling of sorted CD4+ and CD8+ tumor-infiltrating lymphocytes (TILs) from bulk tumors of CRC patients with varying disease stages." (PMID 33916009, 2021). "The ability of CXD101 to affect immune‐relevant gene expression coincided with changes in the tumour microenvironment (TME), especially in the subgroups of CD4 and CD8 tumour‐infiltrating T lymphocytes." (PMID 33773029, 2021).
tumor (continued). "CD4 and CD8 receptors were stained in the tumor sections, which had been proved to be crucial molecules of immune system initiation." (PMID 34541546, 2021). "Together with the significant increase in tumor-infiltrating CD3+CD8+ and CD3+CD4+ T effectors, this resulted in enhanced CD4+Teff/Treg and CD8+/Treg ratios in MTR-OralGem-treated mice." (PMID 33920884, 2021). "In the more malignant tumor tissues of the basal-like and HER2 subtypes, the infiltration level of M1 macrophages, activated memory CD4 T cells, and CD8 T cells was significantly higher." (PMID 34277633, 2021). "In detail, we found that all three tumor infiltrating B lymphocytes (TIL-B) subsets, activated or effector memory CD8+ and activated or effector memory CD4+T cells were significantly correlated with IRF4 expression (|r| > 0.3 and P < 0.001)." (PMID 34195096, 2021). "cDC1 was recently shown to prime CD4+ and CD8+ T cells and can be licensed by CD4+ T cells in the setting of tumor-derived antigens." (PMID 34885215, 2021). "A heterogeneous population of tumor‐infiltrating lymphocytes, CD8+ cytotoxic T cells, CD4+ helper T cells, and regulatory T cells (Tregs) are present in the TME." (PMID 33986746, 2021). "Immunofluorescence staining to identify memory T cells in cSCC showed CD45RO colocalizing with CD3+ T cells, as well as with CD4+ and CD8+ cells, and that these CD45RO+ memory T cells were predominantly located in the stromal areas adjacent to tumor nests." (PMID 33479027, 2021). "Data on the tumor microenvironment of platinum-resistant OC showed low CD8 + T cell infiltration and highly activated CD4 + T cells." (PMID 34454562, 2021). "It interacts with the transmembrane glycoprotein CD200, which can be expressed on a variety of cells, including CD4+ and CD8+ T cells and tumor cells." (PMID 33918618, 2021). "CD4 T-cell help was critical to achieve the optimal expansion and cytolytic activity of tumor-reactive CD8 T cells in the context of vaccination with tumor neoantigens, or immune checkpoint blockade with anti-PD-1 and/or anti-CTLA-4." (PMID 34201655, 2021). "Unexpectedly, we found that NK cell depletion was equally as effective as CD4+ and CD8+ T cell depletion at reversing the anti-tumor effect of VTX + CTX." (PMID 33452311, 2021). "Recent work on tumor immune microenvironment demonstrated that WHO grading in meningioma negatively correlates with the proportion of CD4+, CD8+, and PD-1+ lymphocytes, along with increased numbers of Treg (FOXP3+) cells in the tumor." (PMID 33611710, 2021). "To explore the effect of YM101 on T cell infiltration, we performed anti-CD3, anti-CD4, anti-CD8 IHC staining assays using EMT-6 tumor samples." (PMID 33593403, 2021). "In summary, we concluded that tumor treatment with SFV/IFNg led to an increase in Th and CTL cells and a decrease in T-regs in the CD4+ cell population." (PMID 34835178, 2021). "When compared to healthy liver tissue, the amount of Bregs was elevated while the level of CD4+ CTLs expressing granzyme and perforin was downregulated in HBV tumor tissue, according to Xue’s group." (PMID 34566989, 2021). "We then detected the abundance of CD3+, CD4+, CD8+, Granzyme B+ and F4/80+ cells in the tumour by immunohistochemistry and flow cytometry." (PMID 34732697, 2021). "Anti-CD4 and anti-CD8 fluorescence imaging of the tumor tissue confirmed the remarkably increased T cell infiltration." (PMID 33391476, 2021). "Vascular normalization results in a more homogeneous distribution of functional tumor vessels facilitating CD4+ and CD8+ T-cell tumor infiltration." (PMID 33869665, 2021). "Notablely, compared with the control group, the combined treatment of HT and PLB increased the infiltration of CD4+ T and CD8+ T cells in the tumor tissues of tumor-bearing mice." (PMID 34858184, 2021).
tumor (continued). "These antigen-specific CD4+ T cells enhanced the efficacy of anti-tumour CD8+ T cell responses, and mediated long-lived protection against subsequent tumour re-challenge in mice that survived primary tumour challenge." (PMID 32457487, 2021). "As a tumor develops, the enrichment of IL-4 and IL-13 produced by tumor cells and CD4+ T cells in the TME results in the polarization of TAMs towards an immunosuppressive phenotype, that promotes tumor growth, malignancy, and metastasis." (PMID 34112755, 2021). "Investigating immune cells in the tumor revealed that [Pyr1]Apelin-13 infusion induced the accumulation of CD8+ and CD4+ T cells in central areas." (PMID 34234274, 2021). "PRGN-2009 monotherapy in the syngeneic TC-1 model also reduced tumor volumes and weights, generated high levels of HPV16 E6–specific T cells, and increased multifunctional CD8+ and CD4+ T cells in the tumor microenvironment." (PMID 33651712, 2021). "As expected, the infiltration of CD3+ T cells, CD3+CD8+ T cells, CD3+CD4+ T cells, activated neutrophils (CD11b+Ly6G+ cells), and DCs (CD11c+ cells) were all significantly elevated in MC38 tumor tissues after s.c." (PMID 33824314, 2021). "Upon tumor antigen presentation, CD8+ CTLs, with the help of CD4+ T cells, acquire the killing capacity for tumor elimination." (PMID 34571733, 2021). "On the other hand, tolerogenic DCs produce CD8+CD28+ and CD4+CD25+CTLA-4+ Tregs under the induction of HLA-G, which further strengthens the ability of immune escape of tumor cells." (PMID 34868081, 2021). "Some immune cells in the tumor microenvironment (TME), including dendritic cells (DC), CD8+ and CD4+ T lymphocytes, and NK cells, also play an important role in cancer initiation and progression." (PMID 34367941, 2021). "This, when paired with anti-PD-L1, increased IFNγ production, CD4+ and CD8+ T cell proliferation, tumor regression, and overall survival." (PMID 34975924, 2021). "In the context of tumor therapy, an inverse ratio of intratumoral effector CD8+/CD4+ T cells to immune-suppressive Tregs can be a prognostic factor for better overall survival." (PMID 34885215, 2021). "Similar to EATL, tumor cells in MEITL are typically CD3+, CD5−, CD7+, CD4−, TIA-1+, granzyme B+, perforin+, and CD103+." (PMID 34830926, 2021). "IL-6 is considered one of the important cytokines in MDSC infiltration and regulation, as indicated in a study that showed that IL-6 inhibition in tumor-bearing mice depletes MDSCs and increases IFN-γ production by CD4+ and CD8+ T cells." (PMID 34163519, 2021). "After tumor purity correction, we found that NFE2L3 expression levels were negatively correlated with the infiltration level of CD4 T cells and significantly positively correlated with the infiltration level of CD8 T cells." (PMID 34783304, 2021). "Neoantigen-specific T cell responses were observed in patients who did not receive dexamethasone and multiplex immunofluorescent staining of tumor specimens revealed increased CD8+ and CD4+ T cell infiltration in these responsive patients." (PMID 34054867, 2021). "In fact, in GBM patients, it is common for the numbers of CD4+ and CD8+ T cells to decrease within the tumour and in the circulation." (PMID 33964937, 2021). "To confirm the role of CRNDE in CRC tumor growth in vivo, we constructed AAV vectors (AAV-CD4-shCRNDE-h and AAV-CD4-scrambled), which were specifically expressed in CD4+ T cells." (PMID 33495437, 2021). "In this subgroup of pMMR CRC, the higher TGF-β levels produced by CAFs lead to the exclusion of CD4+ and CD8+ T cells from the tumor center and, therefore, to ICIs inefficacy." (PMID 34110510, 2021). "It is expressed in activated CD4 positive and CD8 positive T cells, NK cells, B cells and monocytes, as well as in some tumor cells and tumor infiltrating lymphocytes." (PMID 34456725, 2021). "The results suggested that CD4, CD53, EVI2b, PLEK, and SASH3 correlated with tumor purity, immune score, CD8+ T cells, and clinical phenotypes." (PMID 34234827, 2021).
tumor (continued). "To this end, we measured by IFN-γ ELISpot the CD4 T cell response directed against telomerase (TERT), a shared-tumor antigen." (PMID 34144673, 2021). "In turn, CD8+ T cells require the functional activities of CD4+ T helper cells, which interact with a range of immune cells, such as antigen presenting cells (APC) and macrophages that present tumor antigens in the context of HLA class II molecules." (PMID 33912442, 2021). "RBCK1 was highly expressed in different cells in the tumor immune microenvironment (TIME), including CD4+ and CD8+ T cells, monocytes, macrophages, and NK cells." (PMID 34795663, 2021). "CD4 TEFF cells can similarly produce cytokines to limit tumour growth, activate anti-tumour functions of other cells such as macrophages, and augment CD8 T cell responses through provision of CD4 T cell help." (PMID 34899742, 2021). "Imatinib-sensitive KIT mutant tumors contained greater frequencies of CD3 + and CD8 + T cells, but a lower percentage of CD4 + T cells and T regs compared to imatinib-resistant KIT mutant GIST tumor mouse models." (PMID 33402214, 2021). "The results above delineate the alteration of SPTBN2 and BCL2L1 in view of tumor immune modulation mediated by CCL27 and CCR10, resulting in a reduced abundance of CD4+ T cells and dendritic cells." (PMID 34179092, 2021). "Oleandrin treatment increased the number of tumor infiltrating CD45+ cells including CD11c+ DCs, CD4+ T cells, and CD8+ T cells." (PMID 33762577, 2021). "A total of 4523 genes in the macrophage samples, 880 in the CD4+, and 1374 genes in the CD8+ T cell samples were significantly, differentially expressed between samples from tumor and from healthy tissue (adjusted p-value < 0.05)." (PMID 33918618, 2021). "The combined therapy increased the number of tumor-infiltrating IFN-γ/TNF-α-producing CD4 and CD8 T cells and delayed tumor growth, as compared to the effect observed in groups treated with c-di-GMP or IRE alone." (PMID 33575350, 2021). "The proportion of proliferating immune cells was higher in HR- as compared with HR+ tumours (Wilcoxon, CD3+P = 0.007; CD8+P = 0.011; CD4+P = 0.009) except for Foxp3+ (P = 0.710)." (PMID 33742063, 2021). "In the tumor microenvironment of patients with TNBC, CD11c positivity correlates with CD4+ and CD8+ T cells." (PMID 34235182, 2021). "TIGIT is overexpressed on either peripheral T cells and tumor-infiltrating CD8+ and CD4+ T cells in HNSCC patients." (PMID 33804419, 2021). "It was demonstrated that the cooperation of CD4+ and CD8+ T cells enhances high-avidity tumor, antigen-specific CTLs, and improves the clinical response to cancer immunotherapy." (PMID 34062821, 2021). "Though peripheral T cells, particularly CD4+ T cells can secrete LAIR2, it is important to know the origin of LAIR2 within tumor tissue T cells." (PMID 35008369, 2021). "In contrast, untreated mice displayed higher frequencies of CD4+, HLA-DR+, and CD279+ T cells in the tumor microenvironment." (PMID 33498319, 2021). "On the sample level we detected excluded (tumor, CD8) and excluded (tumor, CD4) to be the most frequent TIPs in the cohort." (PMID 33791196, 2021). "It is a well-known fact that immune cell infiltration such as CD4+ naive T cells, CD4+ memory T cells, CD8+ T cells, CD8+ Tcm, B cells, and memory B cells in the TME are the key regulators of the tumor development and OS of the GC patients." (PMID 35096022, 2021). "The fraction of proliferating (Ki67+) cells for all four immune cell subpopulations (CD3+, CD4+, CD8+, Foxp3+) was numerically higher in basal-like tumours, whereas luminal tumours showed the lowest fraction of proliferating cells." (PMID 33742063, 2021). "Our recently published work has shown that interleukin (IL)-21-producing CD4+ T cells help to generate effector CD8+ T cells within the tumor, which results in enhanced tumor control." (PMID 33809259, 2021).
tumor (continued). "There were more CAFs and macrophages, but fewer B cells, CD4+T cells, CD8+T cells, and endothelial cells in the tumor tissues than normal controls." (PMID 33588380, 2021). "For example, the presence of CD8+ and CD4+ T cells could improve clinical outcomes and prolong survival in different cancers, while T cell regulation (Tregs) may inhibit antitumor immune response and support the establishment of immune hyporesponse microenvironments in some tumor types." (PMID 33860055, 2021). "An increase in CD4 and CD8 T lymphocytes was detected in the tumor microenvironment and the draining lymph nodes of treated mice." (PMID 33920699, 2021). "cDC1s are critical for eliciting anti-tumor CD8+ T cell responses and T helper 1 (TH1) responses, cDC2 for CD4+ T cell response, and pDC for producing large amounts of type I IFN." (PMID 33648605, 2021). "Nb tumors in p50(f/f);Lys‐Cre hosts have greater numbers of total and activated CD4+ and CD8+ T cells, and depletion of these T‐cell populations obviates slowed tumor growth." (PMID 33480449, 2021). "While the presence of ICOS+ TA-Tregs in TILs were correlated with a poor prognosis in human tumors, effector CD4+ICOS+ T cells were found to be enriched in the peripheral blood and tumor tissues of patients treated with anti-CTLA-4 antagonistic mAbs." (PMID 33924428, 2021). "The anti-tumor immunological response possibly arises from activation of the dendritic cells along with an increase in the CD4+, CD3+ as well as the ratio of CD4+/CD8+ cells in the blood." (PMID 34139452, 2021). "CD25 and CD69 staining revealed a higher expression in CD4+ and CD8+ subsets in the BM compared to the spleen, which correlated with observed tumor burden." (PMID 33414484, 2021). "We examined the expression of immune checkpoint components in both tumor-infiltrating immune cells, i.e., CD4 T, CD8 T, NK, and Treg cells, and the complementary antigen-presenting cells (APCs), i.e., macrophages and tumor cells." (PMID 34140495, 2021). "It was previously reported that regulatory T cells (Treg) with CD4+ and CD25+ are the most significant immunosuppressive cell groups in the tumor microenvironment." (PMID 35071004, 2021). "While the anti-tumor role of CD8+ is generally accepted, the role of CD4+ T cells in cancer immunity is controversial." (PMID 33842331, 2021). "Of note, As the original paper reported, tumor infiltrating Treg and tumor splenic Treg were sorted as live, CD45+TCRb+CD4+Foxp3+CD8-DUMP-)." (PMID 34084175, 2021). "At days 11 and 14, CD4+ and CD8+ tumor-infiltrating lymphocytes (TILs) were analyzed for Nr4a3-Timer, PD1, Lag3, and Ifng-YFP expression." (PMID 34534438, 2021). "PLOV-PTT stimulated maturation of DCs and infiltration of CD4+ and CD8+ T cells in tumor tissues was observed, revealing distinctly higher infiltration of tumor-infiltrating lymphocytes on the 5th day as compared to the 10th day post-PTT." (PMID 34930285, 2021). "In mouse tumor models, agonist antibodies to TNF-R induced a marked increase of antigen-specific CD8+ and CD4+ T cell responses and generated memory T cells." (PMID 33763071, 2021). "This is due to factors that hamper the immune response against cancer, such as the excessive and aberrant presence of CD4 T and CD8 T cells in the tumor microenvironment." (PMID 34681768, 2021). "The CD4+ T cells are able to eliminate tumors resistant to CD8+ T cell-mediated rejection, while the successful anticancer effect leading to tumor rejection is mediated by cooperation between CD8+ and CD4+ T cells." (PMID 34439305, 2021). "Intra-tumor combined administration of SLC and anti-CD25 mAb significantly reduced the frequency of Treg and increased the number of CD8+ and CD4+ T cells in tumor sites, and also maximally inhibited the growth and invasion of HCC." (PMID 34869376, 2021).